CASP8 (caspase 8)
Diseases named in the same sentence as CASP8 in open-access papers (continued):
Sharing a sentence is not in itself a finding about the gene and the disease.
tumor (continued). "Suppose bispecific antigen-targeting CAR-T has a higher potential to activate bystander Fas/caspase-8 in avidity-mediated killing in heterogenous tumor beds." (PMID 37838774, 2023). "According to the obtained results of the present study, CASP8 expression was significantly elevated in the ECSA tumor tissues when compared with the adjacent healthy tissues through RT‐qPCR and WB analyses." (PMID 36533709, 2023). "At the same time, the mRNA level of the CASP8 gene was also increased in tumor cell samples that were cultured with native CIMVs (by 2 times) and CIMVs-BFP (by 2.2 times) (n = 3, **** p < 0.0001), but not as significant as in the case of CIMVs-TRAIL." (PMID 36661524, 2023). "Other studies have shown a similar correlation between CASP8 mutations and FASLG expression in HNSCC tumours with a high level of immune infiltration." (PMID 37443405, 2023). "RT-PCR analysis revealed the presence of RNA coding for caspase 3 and caspase 8 in the majority of EVs derived from the tumor cell lines." (PMID 37297006, 2023). "Activated caspase-8 promotes the activation of caspase 3 in the process of inducing apoptosis, leading to secondary necroptosis or pyroptosis, and thus inhibiting tumor growth." (PMID 37171396, 2023). "The lncRNA PVT1/hsa-miR-16-5p/CASP6/CASP8 regulatory axis plays an vital role in regulating the anti-tumor immune responses for PAAD." (PMID 36882663, 2023). "Caspase-3, caspase-8, and caspase-9 expression were evaluated in tumor specimens by immunohistochemistry assays to assess apoptosis in treated and control groups." (PMID 37720338, 2023). "Overall, these data reinforce the idea that Caspase-8 phosphorylation sustains tumor growth through the upregulation of the inflammatory pathway concurring with the establishment of a pro-angiogenic state and sustaining resistance to therapy." (PMID 37444381, 2023). "An increase in the level of activated caspase 8 in the tumor cells after administration of CIMVs-TRAIL was also confirmed at the protein level." (PMID 36661524, 2023). "Consistent with the in vitro cell experiments, we observed that PTP 9 and anti-PD-1 cotreatment induced a significant increase in tumor expression of Cxcl11, Ccl5, Stat1, Stat3, Tap1, Irf1, Casp8, and Pdl1, compared with anti-PD-1 treatment alone." (PMID 36968224, 2023). "CASP8 expression was negatively correlated with dendritic cells and uncorrelated with tumor purity, CD4+ T cells, and neutrophils." (PMID 36533709, 2023). "In vivo, combination treatment induced a significant antitumor effect with an obvious regression in tumor size and a remarkable and significant expression of caspase-3, caspase-8, and caspase-9 compared to monotherapies." (PMID 37720338, 2023). "It promotes tumor cell migration and inhibits Fas induced apoptosis by assembling caspase-8/RIPK1/FADD/cFLIP complex." (PMID 37171396, 2023). "Unlike targeting antigen-directed CAR-T bystander function of Fas activation, E09-FasL-directed Fas activation (in terms of caspase-8 activation) was directly proportional to Fas expression in tumor cells." (PMID 37838774, 2023). "Griffith and colleagues showed, using a TRAIL-expressing adenovirus, that the rapid expression of TRAIL protein in tumor cells triggered apoptosis via caspase-8 activation." (PMID 37865660, 2023). "We also analyzed the level of a key protein involved in the process of extrinsic apoptosis CASP8 in the tumor tissue." (PMID 36661524, 2023). "Conversely, MLKL and CASP8 were significantly lower in tumor tissues compared to normal tissues (KIRC BLCA LUSC LUAD, etc.)." (PMID 37000317, 2023). "Birinapant was found to target TRAF2-related cIAP, activate caspase-8 and induce tumor cell death by eliminating TNF-induced NF-κB activation." (PMID 37415241, 2023).
tumor (continued). "HCA showed low activation of CASP3 and CASP8, ranging between 0–6% and 0–10% of the tumour (keratin 14‐positive) area respectively." (PMID 37443405, 2023). "For example, in ovarian cancer, low Caspase-8 expression levels correlate with chronic inflammation, immunoediting, and immune resistance, thereby sustaining tumor aggressiveness." (PMID 37444381, 2023). "Among them, CASPASE-8 (CASP8), as a critical protein of multiple cell death pathways, has a dual role in tumor formation and progression." (PMID 37501725, 2023). "In examining the tumor microenvironment, CASP8 showed significant correlations with various immune cell types, suggesting its influence on the immune landscape in HCC." (PMID 38186679, 2023). "Suppression of cFLIP expression in tumor cells induces caspase-8-dependent apoptosis both in vitro and in vivo and sensitizes these cells to TRAIL." (PMID 35115486, 2022). "Nevertheless, the role of caspase-8 in tumor progression and response to therapy remains controversial." (PMID 36428594, 2022). "Deciphering the cellular localization of TRAIL-R2 that results in caspase-8 activation and apoptosis in glutamine-deprived tumor cells is an issue that requires further investigation." (PMID 36302756, 2022). "The ratios of cleaved caspase-9 to caspase-9 in tumor tissues derived from all treatment groups were significantly higher than those in the control group, whereas those of caspase-8 differed little among all groups." (PMID 35336106, 2022). "The largest regulatory network they found included ERCC1, PARP, Snail, c-Met, Caspase-8, and Rb, but connections to RB were reduced in a subgroup that showed tumor progression." (PMID 35672443, 2022). "We demonstrate that restricting glutamine utilization in tumor cells induces a GCN2-dependent signaling pathway leading to TRAIL-R2 upregulation that together with GCN2-independent FLIP downregulation results in caspase-8 activation and apoptotic cell death." (PMID 36302756, 2022). "To confirm that ANGPTL4 can regulate the occurrence of pyroptosis and apoptosis through the NLRP3\ASC\Caspase 8 pathway, we used tissue proteins from the xenograft tumor to re-verify the results." (PMID 36467503, 2022). "The CASP8 and MAPK1 genes had a strong correlation with 9 tumor-associated cellular pathways, but there was only one pathway difference between the two." (PMID 36193082, 2022). "Similar results were evident in the present study, in which the genetic expression of three genes (AIM2, CASP6, and CASP8) was upregulated in tumor tissues and was validated as protective factors in the multivariate Cox regression analysis." (PMID 35846123, 2022). "The Weighted Score (WS) of Caspase-8 expression revealed a significant correlation with pCDK9 levels in corresponding tumor tissues (p = 0.05)." (PMID 36399280, 2022). "For Rnf31 we demonstrate that it protects tumor cells from TNF-mediated caspase 8 cleavage and subsequent apoptosis induction, a mechanism that is conserved in human PDA organoids." (PMID 35379808, 2022). "In tumors, IFN-γ acts as an effective apoptosis-inducing factor by directly inducing caspase-1 and caspase-8 in tumor cells." (PMID 36712869, 2022). "The present study revealed that CASP8 expression was strongly positively associated with the activation of most immune cells, suggesting the contributory role of CASP8 in regulating tumor immunology in LGG." (PMID 35741587, 2022). "First, our meta-analysis revealed that Caspase-8 expression levels correlate with tumor development and clinical outcome." (PMID 36399280, 2022).
tumor (continued). "We also detected DR5 and Caspase 8 protein expression in mice tumor tissue and obtained consistent results at the cellular level." (PMID 36034825, 2022). "Together, these results indicate that cFLIP downregulation is one of the earliest events observed in the signaling pathway leading to caspase-8 activation in tumor cells undergoing ER stress." (PMID 35115486, 2022). "TRAIL was shown to induce caspase-8-dependent apoptosis in tumour cells by binding to death receptors 4 or 5 (DR4, TRAIL-R1, or DR5, TRAIL-RII)." (PMID 36011012, 2022). "In AOM-induced colon tumors in rats was documented that bLf had chemopreventive activity by its apoptotic ability on tumor cells resulting from the increased Fas expression as well the activation of caspase-8 and -3." (PMID 35264972, 2022). "For example, the inhibition of caspase-8 can significantly enhance activation of the ZBP1-MLKL pathway in tumor cells after radiotherapy and promote mitochondrial damage to release mtDNA." (PMID 35326602, 2022). "In the primary tumor group, CASP8 had a lower methylation level than that in the normal group, although the number of samples varied considerably between the two groups." (PMID 36466844, 2022). "Silencing of caspase-8 expression markedly reduced the sensitivity to glutamine starvation in both tumor cell lines." (PMID 36302756, 2022). "Particularly in the presence of a stimulus such as TNF, chemotherapy or TLR ligand this results in the formation of a RIPK1: caspase-8 complex, caspase-8 activation and the induction of tumor cell death." (PMID 34572737, 2021). "Caspase-8 plays therefore an essential role not only in the primary tumor cells but also in the TME by regulating the immune response, B and T lymphocyte activation, and macrophage differentiation and polarization." (PMID 33026575, 2021). "Using these cell lines to induce xenograft tumors in nude mice, we show that low Caspase 8 cells induced more rapidly growing subcutaneous tumors and that in vivo combination treatments reduced both Caspase 8-high and Caspase 8-low tumor growth." (PMID 34088893, 2021). "Meanwhile, the chemotherapeutic agent trabectedin activates caspase-8-dependent apoptosis in monocytes and macrophages, and results in the reactivation of tumor-infiltrating lymphocytes that secrete cytotoxic molecules to promote tumor cell death." (PMID 34201127, 2021). "Activated caspase-8-dependent apoptosis in TAMs, and resulted in the reactivation of tumor-infiltrating lymphocytes that promote tumor cell death." (PMID 34201127, 2021). "Three apoptotic markers included general apoptosis protein-activated caspase-3, extrinsic apoptosis protein-activated caspase-8, and intrinsic apoptosis protein-activated caspase-9 in the tumor section were all markedly increased by imipramine and erlotinib." (PMID 34765548, 2021). "This nuclear accumulation of caspase-8 was reported also in HPV-positive tumour cell lines and cervical cancer." (PMID 33602906, 2021). "Taken together, these findings indicate that expression of WT or MT caspase-8 by HNSCC tumor cells alters the tumor immune microenvironment." (PMID 34362880, 2021). "The relative protein expression of NOV, JNK, AP-1, Caspase 8, and Caspase 3 in tumor tissues in tumor cell xenotransplantation nude mouse model was examined by western blot." (PMID 35201461, 2021). "Markedly increased metastatic incidences and extended tumor distributions were observed in the mice inoculated with A549 + control shRNA cells and H522 + Casp8 WT cells, which corresponded with worse OS." (PMID 34367939, 2021). "This study used various high-affinity pre-clinical and clinical DR5 agonist antibodies that activate caspase-8 and tumor cell death." (PMID 34731630, 2021). "In immunocompetent C57BL/6J mice, we found that knocking down Casp8 significantly promoted tumor growth and led to increased tumor volume." (PMID 33934451, 2021).
tumor (continued). "Many annexin family proteins, including Anxa3, have been shown to inhibit apoptosis in tumor cells due to caspase-3 and caspase-8 repression (the result of Anxa3/JNK pathway activation)." (PMID 34204832, 2021). "The immunoreactivity score indicated the significant higher expression of cytoplasmic caspase-8 in tumor samples than in BPH tissues (P < 0.0001)." (PMID 34482382, 2021). "Similar to our results, treatment with DHA markedly activated FasL, cleaved caspase-3, and cleaved caspase-8 in the lung metastasis model, supporting the assumption that tumor death occurred in a manner consistent with apoptosis in this study." (PMID 34539408, 2021). "CASP8, which was the fourth most frequently inactivated gene, is a surprising new candidate for tumor suppressor." (PMID 34070941, 2021). "Lastly, our immune studies are preliminary in nature and only allow us to conclude that the tumor microenvironment differs with the expression of WT or MT caspase-8." (PMID 34362880, 2021). "As measured by bioluminescence, mice implanted with A549 + control shRNA cells and H522 + Casp8 WT cells had a significantly increased tumor burden, and metastasis occurred in all 10 mice in the group." (PMID 34367939, 2021). "Some studies have shown that ROS can also cause exogenous apoptosis mainly by increasing the sensitivity of tumor cells to Fasl, then activating caspase-8 to mediate exogenous apoptosis through the death receptor Fas/Fasl pathway." (PMID 33994999, 2021). "The increased expressions of cleaved caspase-8 and cleaved caspase-3 were further confirmed by immunofluorescence staining and western blotting on tumor tissues in IRAK2-overexpressed xenografted mice treated with RT." (PMID 34249686, 2021). "Here we show that combination treatment with a Smac-mimetic can target tumor cells with low Caspase 8 and induce necroptotic cell death." (PMID 34088893, 2021). "Previous studies have revealed that chemotherapeutic agents such as anthracyclines and oxaliplatin can induce ICD in tumor cells via caspase-8-dependent pathway." (PMID 33762577, 2021). "Lastly, future efforts to develop therapies that potently eliminate caspase-8 mutant tumors should focus on identifying the specific vulnerabilities of these tumor cells." (PMID 34362880, 2021). "Immunoblotting of tumor lysates revealed successful DOX induction of WT or MT caspase-8 tumors in most of the treated mice." (PMID 34362880, 2021). "The impact of a representative caspase-8 mutant on the tumor microenvironment in a syngeneic, immunocompetent mouse model of HNSCC was also investigated." (PMID 34362880, 2021). "In a subcutaneous tumor growth model, mice were inoculated with either high Caspase 8 or Caspase 8-depleted cells in order to induce palpable tumors." (PMID 34088893, 2021). "HMWp activated expression of caspase-8 and -9 enzymes, and pro-apoptotic Bax protein whilst inhibiting expression of tumor survivor protein, Bcl-2." (PMID 32832273, 2020). "There was only one study, which included 11 patients with stage 4 NB and found that CASP8 is methylated in 91% of tumor samples." (PMID 33381579, 2020). "This suggests a growth advantage of tumor cells with high expression of caspase-8 in the pathogenesis of CRC, which is consistent with previous studies." (PMID 32102251, 2020). "Association between CASP8 methylation and known risk factors such as MYCN amplification, tumor stage, and age at diagnosis was studied in previous studies." (PMID 33381579, 2020). "Because of the key role it plays in death receptor–mediated apoptosis, CASP8 has long been considered a tumor suppressor gene." (PMID 33108350, 2020). "Based on these assumptions, it is now believed that caspase-8 can behave as tumor suppressor or proto-oncogene." (PMID 35047986, 2020).
tumor (continued). "The radiation plus birinapant combination further reduced in vivo tumor growth and provided survival benefit in both the control and Casp8-knockdown animal cohorts." (PMID 33108350, 2020). "Taken together, our results support that tumor encounter modifies the TNF/RIPK3-dependent induction of caspase-8 activity to TNF/RIPK3-dependent caspase-1 activity after PH." (PMID 33178579, 2020). "Western blot analysis showed that combination treatment leads to substantial changes in the proteins involved in caspase-mediated apoptosis of tumor cells, in particular, caspase-3, caspase-8 and caspase-9 cleavage and subsequent PARP cleavage." (PMID 32019988, 2020). "On the other hand, high expression of the caspase 8 (CASP8) and lymphocyte-specific protein 1 (LSP1) genes are associated with tumor inhibition in most cases." (PMID 33112566, 2020). "In the tumor stroma, a decrease of M1 macrophages, an induction of M2 macrophages and an upregulation of miR-7e-5p downstream targets (FasL, Caspase 3 and Caspase 8) were detected in high-grade FL." (PMID 33168041, 2020). "Treatment with radiation alone significantly inhibited in vivo tumor growth and improved survival in both the control and Casp8-knockdown animal cohorts." (PMID 33108350, 2020). "in tumor cells, degradation of the apoptotic initiator caspase 8 by autophagywas observed, resulting in reduced cellular stress and apoptosis." (PMID 30909829, 2019). "ITCH and USP8 silencing experiments highlighted the role of this ubiquitination/deubiquitination process in modulating 9F7-F11-induced c-FLIP and HER3 degradation, and also in the inhibition of caspase-8-mediated apoptosis of tumor cells." (PMID 31443721, 2019). "We found that 9F7-F11 sensitizes tumor cells to DR5/caspase-8-mediated apoptosis through ITCH-dependent downregulation of c-FLIP." (PMID 31443721, 2019). "Here, we report that ITCH-dependent proteasomal degradation of c-FLIP induced by the anti-HER3 antibody 9F7-F11 favors DR5/caspase 8-mediated apoptosis of tumor cells." (PMID 31443721, 2019). "The western blot assay and immunohistochemistry studies showed that the expression of Caspase-3, Caspase-8, and Bax in tumor tissues were significantly increased in a dose-dependent manner, while the expression of Bcl-2 was undetectable." (PMID 30651572, 2019). "Specifically, ITCH silencing or CI blocked 9F7-F11-induced caspase-8-mediated apoptosis of tumor cells, and restored c-FLIP expression." (PMID 31443721, 2019). "In the context of TNFR1 signaling, priming of tumor cells with TWEAK enhances TNF-induced caspase-8 activation and apoptosis." (PMID 31885495, 2019). "High expression of c-FLIP can block Caspase-8 and makes tumor cells resistant to this apoptotic pathway." (PMID 31552181, 2019). "Another group also assessed the levels of CASP8 expression in tumor in comparison with normal margins of Iranian BC patients, which showed decreased CASP8 expression in tumour tissue." (PMID 31286981, 2019). "For example, tissues located distally from, as well as close to the tumor invasion have higher percentage of cells expressing CASP8 compared to CASP3." (PMID 30019295, 2018). "PRP induced tumor cell apoptosis by inhibiting the Jak1–Stat3 pathway and by activating Caspase-3 and Caspase-8 to increase the Bax/Bcl-2 ratio." (PMID 29735884, 2018). "We confirm that trabectedin activates an extrinsic apoptotic pathway in senescent tumor cells, as demonstrated by enhanced surface Fas, activation of caspase-8 and downstream mitochondrial depolarization." (PMID 29731994, 2018).